NDST2 (N-deacetylase and N-sulfotransferase 2)
Description:
Essential bifunctional enzyme that catalyzes both the N-deacetylation and the N-sulfation of glucosamine (GlcNAc) of the glycosaminoglycan in heparan sulfate. Modifies the GlcNAc-GlcA disaccharide repeating sugar backbone to make N-sulfated heparosan, a prerequisite substrate for later modifications in heparin biosynthesis. Plays a role in determining the extent and pattern of sulfation of heparan sulfate. Required for the exosomal release of SDCBP, CD63 and syndecan.
Synonyms: N-HSST 2; HSST2; NST2
Tractability: Antibody: UniProt predicts a signal peptide or a membrane-spanning region. PROTAC: its protein half-life has been measured.
Gene: Protein-coding gene on chromosome 10 (73,801,910 to 73,811,963, reverse strand). Ensembl gene ENSG00000166507.
Subcellular location: Golgi apparatus membrane
Subcellular location (Human Protein Atlas): Cytosol
Pathways (Reactome):
Metabolism: HS-GAG biosynthesis
Gene Ontology:
Molecular function: heparan sulfate N-deacetylase activity; deacetylase activity; heparan sulfate N-sulfotransferase activity; N-acetylglucosamine deacetylase activity; hydrolase activity; sulfotransferase activity
Biological process: heparan sulfate proteoglycan biosynthetic process; heparin proteoglycan biosynthetic process
Cellular component: Golgi apparatus; Golgi membrane; membrane
Genetic constraint (gnomAD): Loss-of-function variants: 31 observed, 87.29 expected, observed/expected ratio (o/e) 0.36, 90% interval 0.27 to 0.48. The upper end of that interval is the gene's LOEUF score, 0.48, which puts it in group 2 of 6, group 1 being the genes least tolerant of losing a copy. Missense variants: 943 observed, 1,182.9 expected, observed/expected ratio (o/e) 0.8, 90% interval 0.75 to 0.84. Synonymous variants: 406 observed, 456.06 expected, observed/expected ratio (o/e) 0.89, 90% interval 0.82 to 0.97.
Homologues: Orthologues: chimpanzee NDST2 (99% identical), macaque NDST2 (99% identical), rabbit NDST2 (97% identical), mouse Ndst2 (97% identical), guinea pig NDST2 (96% identical), rat Ndst2 (96% identical), dog NDST2 (90% identical), pig NDST2 (89% identical), tropical clawed frog ndst2 (79% identical), zebrafish ndst2b (74% identical), zebrafish ndst2a (67% identical). Paralogues in human: NDST1 (70% identical), NDST4 (67% identical), NDST3 (64% identical), HS3ST2 (13% identical), HS3ST3A1 (13% identical), HS3ST3B1 (13% identical), HS3ST4 (13% identical), HS3ST6 (11% identical), HS3ST5 (11% identical), HS3ST1 (10% identical).
Diseases named in the same sentence as NDST2 in open-access papers:
NDST2 is named in the same sentence as 17 diseases in open-access papers, as found by Europe PMC text mining. Sharing a sentence is not in itself a finding about the gene and the disease. The quoted sentences say what the papers report.
periodontitis (2 papers, 2019 to 2024). An acute or chronic inflammatory process that affects the tissues that surround and support the teeth. "The heparan sulphate biosynthesis enzymes (EXT1, EXT2, NDST1, and NDST2) displayed comparable correlation with the gingival tissue inflammatory infiltrate in the periodontitis group (EXT1, EXT2 and NDST1 correlated positively, and NDST correlated negatively)." (PMID 38674142, 2024).
atherosclerosis (1 paper, 2020). A disease characterized by the build-up of fatty material and calcium deposition in the arterial wall resulting in partial or complete occlusion of the arterial lumen. "Inactivation of NDST2 may impact the atherosclerosis by altering the structure of monocytes/macrophages heparan sulfate (HS), while also alter the glomerular HS to impact the primary kidney diseases." (PMID 33343632, 2020).
femoral neck fracture (1 paper, 2024). Fractures of the short, constricted portion of the thigh bone between the femur head and the trochanters. "The immunohistochemical expressions of SDC1, SDC2, SDC4, EXT1, EXT2, NDST1 and NDST2 in synovial intima and subintima were then analysed and compared with the control group (patients with femoral neck fracture)." (PMID 38674142, 2024).
melanoma (1 paper, 2017). A malignant, usually aggressive tumor composed of atypical, neoplastic melanocytes. "As an alternative scenario explaining for the effect of NDST2 on melanoma, it is noteworthy that heparin is crucial for promoting the storage of MC proteases, including Mcpt4, Mcpt5, Mcpt6 and Cpa3." (PMID 28212574, 2017). "Interestingly, it was shown in a previous study, utilizing a subcutaneous model of melanoma, that mice with defective expression of NDST2 developed larger metastatic lesions than did WT mice." (PMID 28212574, 2017).
metastatic tumors (1 paper, 2018). "The tissue distribution of NDST1 and NDST2 broadly overlap, and transcripts for both were detected in all samples analyzed in this study, with NDST2 appearing downregulated in all LSCRCs, while NDST1 transcription was downregulated in all metastatic tumors and in 60% of non-metastatic." (PMID 29940912, 2018).
synovitis (1 paper, 2024). Inflammation of a synovial membrane. "Statistically, the expression of NDST2 was significantly lower in the synovial membranes of the controls compared to both the low-synovitis-score and higher-synovitis-score groups (p = 0.001, p = 0.006, respectively)." (PMID 38674142, 2024).
tumor (3 papers, 2005 to 2025). "The demonstrated inhibition of HS biosynthetic system was mainly due to the selective significant suppression of the N-deacetylase/N-sulfotransferases Ndst1 and Ndst2 and sulfatase Sulf2 (-3–3.5-fold) in the tumor tissues." (PMID 37373391, 2023). "In specific, we previously showed that syngeneic tumor cells implanted into NDST-2 knockout mice grew faster than tumor cells implanted into wild-type mice that synthesized normal heparin." (PMID 16176582, 2005).
cancer (2 papers, 2014 to 2021). A tumor composed of atypical neoplastic, often pleomorphic cells that invade other tissues. "Transcriptional patterns of HS-metabolic enzymes (EXT1, EXT2, NDST1, NDST2, GLCE, 3OST1/HS3ST1, SULF1, SULF2, HPSE) were determined in normal, benign, and cancer human prostate tissues and cell lines (PNT2, LNCaP, PC3, DU145)." (PMID 24782989, 2014).
NDST2 also shares sentences with these, for which no sentence is quoted: glioma (2 papers); infection (2); anaplastic astrocytoma (1); astrocytoma (1); autoimmune disease (1); chronic kidney failure (1); glioblastoma multiforme (1); kidney diseases (1); prostate tumors (1).